EGFR (epidermal growth factor receptor)
Diseases named in the same sentence as EGFR in open-access papers (continued):
Sharing a sentence is not in itself a finding about the gene and the disease.
cancer (continued). "EGFR plays a crucial role in the growth, differentiation, and movement of normal and cancer cells." (PMID 38057816, 2023). "Notably, the cytotoxicity of the most active compounds, VM26 and VM25, at an IC50 of 12.6 μM and 14.4 μM, respectively, is similar to that of gefitinib, a well-known anti-EGFR drug in cancer therapy, at an IC50 of 15.2 μM." (PMID 37754201, 2023). "Erlotinib, primarily known for EGFR inhibition in cancer therapy, also interacts with ERRFI1." (PMID 37862243, 2023). "Thus, combination of EGFR trafficking and TKIs presents an understudied area that has potential opportunity to benefit cancer patients with TKI resistance." (PMID 37752992, 2023). "12,33 KRAS-driven cancers are also resistant to therapies targeting RTKs such as EGFR." (PMID 36241718, 2023). "Therefore, promoting the degradation of EGFR is an alternative strategy for targeting EGFR-related cancers." (PMID 37270563, 2023). "This work also showed two microRNAs that have combined effect on EGFR which may have important implications in EGFR related cancers prognosis and therapy." (PMID 37114127, 2023). "Furthermore, M2 TAMs secrete Epidermal Growth Factor (EGF), which binds to EGFR on cancer cells, for activating their growth signaling including MAPK/ERK and PI3K/Akt pathways, promoting cell motility and invasion." (PMID 37965573, 2023). "Two classes of EGFR-targeted cancer therapeutics include monoclonal antibodies (mAbs), which bind to the extracellular domain of EGFR, and tyrosine kinase inhibitors (TKIs), which mostly target the intracellular part of EGFR and inhibit its activity in molecular signaling." (PMID 38201251, 2023). "However, due to differences in cancer trajectories in patients with NSCLC using EGFR-TKIs, understanding patient perceptions regarding oral cancer medications can help tailor evidence-based practice with increasing oncology care." (PMID 37252908, 2023). "Therefore, this study highlights the unique therapeutic potential of AuNP-NmAb in EGFR+ cancers and shows the potential to develop other mAb nanoparticle complexes for a superior therapeutic efficacy." (PMID 37623652, 2023). "In addition, 7D12-NK92MI exhibited more significant immunotherapy efficacy in EGFR-positive cancer cell-bearing mice." (PMID 37514008, 2023). "The binding of galectin-3 to β1,6GlcNAc-branched N-glycans on β4 integrin induces the formation of a supramolecular complex consisting of α6β4 integrin, EGFR, and laminin-332, which in turn promotes cancer cell adhesion and migration via the activation of PI3K and ERK signaling pathways." (PMID 38136623, 2023). "Likewise, higher HiPS scores are observed in cancers expressing the Basal IHC/ISH markers EGFR (in CPS-II and CPS-3, p<0.001) and CK5/6 (in CPS-II, p<0.001)." (PMID 37293118, 2023). "Therefore, the GSDME-EGFR interaction plays an important role in NSCLC development, reveal a previously unrecognized link between GSDME and EGFR stability and offer new insight into cancer pathogenesis." (PMID 37085908, 2023). "However, the overexpression and overactivation of the EGFR in cells can provoke aberrant signaling, leading to the development and progression of cancer." (PMID 37754201, 2023). "Novel EGFR‐LFDs and new cancer types with EGFR‐LFD have been identified." (PMID 36622089, 2023). "In other words, we think those patients might have two subclones of cancer cells, one is driven by EGFR exon 21 p.L858R and the other is driven by EGFR 19-Del, and both of them are likely to be sensitive to EGFR TKIs." (PMID 36829178, 2023). "Increasing evidence suggests that 6-shogaol treatment induces anti-cancer effects via blocking of the EGFR pathway, and EGFR-TKI gefitinib also exerts powerful anti-cancer effects by inhibiting the phosphorylation of EGFR and by activating the ER stress response." (PMID 36768961, 2023). "Signaling pathways triggered by the EGFR protect normal and cancer cells from anoikis." (PMID 37754201, 2023).
cancer (continued). "Recent studies demonstrated the crosstalk between the β2-AR pathway and many other molecular mechanisms in cancer, among which the EGFR, which could be directly activated by the β2-AR." (PMID 37723219, 2023). "The cell-surface-expressed EGFR can be exploited for specific targeting of cancer cells with EVs." (PMID 37686050, 2023). "Radioactively labelled Nbs have been developed for the detection of not only other cancer biomarkers, such as EGFR and fibronectin, but also different diseases such as atherosclerosis—indicating that Nbs have a promising future in the field of in vivo diagnostic methods." (PMID 36983063, 2023). "Despite the different study field and research direction, we substantiated the synergistic effect between GPNMB and EGFR in the non-cancer field and raised that the interaction between the two functioned in the biological processes and cell differentiation in NSCs." (PMID 36820063, 2023). "For the patients without EGFR mutation found in liquid NGS (but with EGFR T790M found in their cancer tissues), 8 (17%) patients received subsequent osimertinib." (PMID 38140788, 2023). "The EGFR/PI3K/AKT/mTOR signaling pathway is a major pathway in diverse types of cancers." (PMID 37631344, 2023). "Additionally, the CD133 and a cancer stem cell marker co-localized with EGFR, increased phosphorylation, and stability of EGFR, acquiring stem cell-like properties that progressed to more malignant GBM37,38." (PMID 37179387, 2023). "Therefore, in the current study, we only evaluated EGFR expression in cancer cells by immunohistochemical analysis in ESCC patients and did not detect its mutation." (PMID 36812484, 2023). "The protein levels of EGFR, independent of its phosphorylation status, is strongly associated with the progression of the disease and a bad prognosis of a variety of types of cancers not expressing mutated EGFR." (PMID 37446288, 2023). "While EGFR is commonly overexpressed in cancer, there is still expression in healthy tissue." (PMID 37315787, 2023). "How cancer cells in PTC would benefit from downregulation of EGFR?" (PMID 37114127, 2023). "We hypothesized that altering levels of acetyl-Sia may affect cancer cell responses to EGFR-targeted therapeutics." (PMID 37687086, 2023). "Another receptor that might take part in the opioid agonists and antagonists effect on cancer cell proliferation, migration, and invasion is the epidermal growth factor receptor (EGFR, also known as erbB-1)." (PMID 36835812, 2023). "Mechanistically, Kremen2 may exert its oncogenic effect by interacting with SOCS3 and blocking the ubiquitin-dependent EGFR degradation, thereby sustaining the EGFR-mediated cancer signaling pathways and promoting cell proliferation and metastasis of NSCLC." (PMID 37270563, 2023). "EGFR regulates a variety of physiological responses, including cell proliferation, apoptosis, and differentiation, and is suspected to have a role in a variety of cancers." (PMID 37474552, 2023). "Abnormal expression of EGFR is closely related to the occurrence of cancer." (PMID 37143582, 2023). "Chronic activation of EGFR may endow cancer cells with oncogenic dependence on EGFR signaling, thereby making them highly susceptible to EGFR TKIs such as gefitinib." (PMID 37834377, 2023). "The EGFR also performs a fundamental function in numerous types of cancers." (PMID 37441462, 2023). "Additionally, in mouse pancreatic KMPC44 cancer cells, fucoxanthinol (5 μM for 1 d) regulated inflammation and growth pathways, including Mapk,Nf-κb, protein kinase C (Pkc),Stat, Tgf-β, and epidermal growth factor receptor (Egfr)." (PMID 37678712, 2023).
cancer (continued). "EGFR copy gains were significantly biased in 9 cancer types including GBM." (PMID 37414817, 2023). "Oncogenic ecDNAs are not just limited to EGFR variants and are likely to apply to most oncogenes across different types of cancer." (PMID 36859558, 2023). "Hence, current therapeutic strategies support the twin suppression of each VEGFR-2, and EGFR represents a promising cancer-fighting strategy." (PMID 36678593, 2023). "Consequently, EGFR inhibition is now recognized as one of the most effective cancer-treatment strategies." (PMID 37764297, 2023). "Therefore, dual treatment with PI3K and EGFR inhibitors is also a therapeutic strategy to avoid cancer-acquired resistance." (PMID 37237486, 2023). "SC4MOL is involved in epidermal growth factor receptor signaling, a pathway upregulated in cancer." (PMID 36958722, 2023). "Among these hallmarks of cancer, the ability of sustaining proliferative signaling is of remarkable relevance in oral oncogenesis, and in this regard, the epidermal growth factor receptor (EGFR) has received singular attention, having been extensively studied." (PMID 37569265, 2023). "In addition, the EGFR-targeting ability of GE11 improved the uptake of nanoparticles in EGFR-overexpressing HCT 116 cancer cells approximately two-fold." (PMID 37237914, 2023). "Moreover, bidirectional signaling between estrogen receptor and EGFR has been demonstrated in many cancer types." (PMID 36802389, 2023). "Multiple types of cancer have elevated EGFR levels, which promote solid tumor growth." (PMID 36676140, 2023). "Moreover, EGFR mutant cancer cells upregulates TGFβ and CCL22 that are important for Tregs polarization and accumulation, and CXCL8, a neutrophil chemoattractant." (PMID 37180110, 2023). "Although the specific regulatory mechanism of GSDME and EGFR requires more study, our findings indicate that the GSDME-EGFR interaction may be a ubiquitous cancer-promoting factor." (PMID 37085908, 2023). "In addition, we identified recurrent CNVs in regions of well-recognized cancer-driving genes (EGFR, MTOR, CCND1, and MYC) or tumor suppressor gene (RB1), with a relatively higher variation in the DN and T stages." (PMID 36914617, 2023). "Moreover, they found that that SESN3 has a prominent role in the induction of apoptosis in epidermal growth factor receptor (EGFR)-mutant cancer cells." (PMID 37284849, 2023). "FLT1 could be described as a therapeutic target in inflammatory events whereas EGFR is known as a key regulator in cell division and cancer development." (PMID 36899812, 2023). "In addition, although EGFR is a potential target for AD treatment, the effectiveness of major anti-cancer EGFR TKIs as AD therapeutics has received little attention." (PMID 37601068, 2023). "To determine whether miR-218-5p exerts its function through its target EGFR, we transiently overexpressed EGFR in As-T expressing miR-218-5p stable cells and then tested cancer-related biological processes." (PMID 36831545, 2023). "As is well known, EGFR is a proto-oncogene that enhances cancer cell proliferation and survival." (PMID 37686097, 2023). "In sum, we found that a novel activating mutation of the axon guidance gene PLXNB2 sustains proliferative autonomy and confers invasive properties to stem cells isolated from cancers of unknown primary, in EGFR‐dependent manner." (PMID 36722641, 2023). "Nitrosamines may enhance cancer progression by upregulating the expression of cyclinE 1, cyclinD 1, transform growth factor α, and epidermal growth factor receptor in esophageal tissues." (PMID 37020268, 2023). "Interestingly, they showed that cancer patients that received targeted therapy that includes the EGFR-tyrosine kinase inhibitors showed the lowest death rate compared to cancer patients who received immunotherapy, chemotherapy, or surgery." (PMID 37112680, 2023). "Hence, EGFR is a known cancer biomarker frequently expressed in LC, while miR-218-5p possesses antitumor activity through EGFR." (PMID 37760496, 2023).
cancer (continued). "Together, these data indicate that targeting retrotranslocation of EGFR may be a potent therapeutic for EGFR-driven cancer." (PMID 36253541, 2023). "Antibody-drug conjugates (ADCs) targeting EGFR have also shown promise in treating certain cancers." (PMID 37720348, 2023). "Using a multifunctional delivery vector, the genome editing plasmid can be specifically delivered into circulating malignant cells in whole blood from cancer patients for robust epidermal growth factor receptor (EGFR) knockout to effectively block cancer cell fusion." (PMID 37590231, 2023). "In addition, TCM and molecular targeted drugs have synergistic anti-cancer effects on lung cancer patients with EGFR-TKI resistance." (PMID 36744262, 2023). "The clinical outcome of cancer patients after receiving anti‐EGFR therapy is known to be diverse." (PMID 37341071, 2023). "EGFR is a widely used marker for the prognosis of many cancers." (PMID 37232831, 2023). "Various therapeutics such as monoclonal antibodies (CetuximabTM, NimotuzumabTM), inhibitors (GefitinibTM, ErlotinibTM) are known to trigger different EGFR signaling pathways to enhance the survival of cancer cells and to develop resistance against therapeutic agents." (PMID 37182181, 2023). "In the England dataset, there were two Cancer Alliance regions (South East London and Thames Valley) with sparse data owing to data unavailability (<5% of lung tumours diagnosed in 2016–2018 have a definitive test result recorded for EGFR)." (PMID 37020004, 2023). "Therefore, we select H1975 (EGFR L858R mutation and ErBb2 activation) and H1650 (EGFR Exon19 deletion and PTEN absence) to study the anti-cancer cell effects of BYL719 and gefitinib in the two NSCLC cell lines." (PMID 37553597, 2023). "Given the significant roles of the EGFR/PI3K/AKT/mTOR pathway in human cancer, there has been a strong emphasis on investigating its clinical potential by targeting the major components of the EGFR/PI3K/AKT/mTOR signaling pathway using specific small-molecule inhibitors." (PMID 37631344, 2023). "So far, oncogenic KDDs are found in BRAF and EGFR across different cancer types." (PMID 36325957, 2023). "Therefore, EGFR has become an important target for therapeutic interventions, and drugs that inhibit EGFR signaling, such as tyrosine kinase inhibitors and monoclonal antibodies, have been developed for the treatment of certain cancers." (PMID 37706181, 2023). "Gefitinib is a medication for cancer that inhibits EGFR in target cells." (PMID 37697969, 2023). "Furthermore, studies have illustrated the interplay between FGFRs and EGFRs in other cancer types, and a combination treatment with EGFR inhibitor, erlotinib, increased the sensitivity to PD173074 inhibition in CCA cell lines." (PMID 37173994, 2023). "EGFR is most well known for its involvement in tumorigenesis and cancer progression." (PMID 38004424, 2023). "EGCG and EGFR-TKI induce apoptosis in a variety of cancer types, including NSCLC, SCCHN and TNBC." (PMID 37762316, 2023). "Estrogen may induce EGFR-TKI resistance in NSCLC cells by acting not only on cancer cells but also on CAFs." (PMID 37509283, 2023). "Adenosine, as the immune-suppressive factor, was overproduced in EGFR-MT cancer cells, which can directly suppress the process of NK cells killing, the maturation of DCs, and the function and proliferation of cytotoxic T cells, although the detailed mechanism(s) remains undetermined." (PMID 36949948, 2023). "The epidermal growth factor receptor (EGFR) signaling pathway plays an important role in carcinoma." (PMID 37228701, 2023). "To determine whether the EMT regulatory signaling pathway is dependent on ABCA1 expression, we identified the most aberrantly activated pathways, including the EGFR, SRC, and ERK pathways, which are associated with ABCA1 in various carcinomas." (PMID 36672209, 2023).
cancer (continued). "While the combination of the analysis of 5′/3′-end RET expression imbalance and variant-specific PCR allowed identification of RET translocations in approximately 2% of consecutive NSCLCs, this estimate approached 120/2361 (5.1%) in EGFR/KRAS/ALK/ROS1/BRAF/MET-negative carcinomas." (PMID 37445709, 2023). "Moreover, EGFR was an upstream regulator of the Ras signaling pathway, and its activation was a major trigger for the progression of most carcinomas." (PMID 36717944, 2023). "Protective autophagy limited the therapeutic effects of EGFR-TKIs in different cancer cells." (PMID 35690866, 2022). "While elevated ErbB signaling is associated with chronic inflammatory disorders, EGFR helps mount innate immune responses and epidermal loss of EGFR or EGFR receptor inhibitors used in cancer treatment elicit adverse inflammatory rashes." (PMID 35686051, 2022). "There are several mechanisms by which cancer cells can obtain increased EGFR expression." (PMID 35160746, 2022). "SW480 is an EGFR-driven cancer cell and harboring KRAS mutant (G12V) instead of G12S in A549." (PMID 35578244, 2022). "However, overall, a major fraction of evidence substantiated the role of betulinic acid in the inactivation of EGFR-driven downstream signaling in different cancers." (PMID 36615262, 2022). "Erlotinib exhibited anti-cancer effects by inhibiting epidermal growth factor receptor (EGFR)." (PMID 35453310, 2022). "Levels of EGFR were found to be reduced in Sp1-knockdown or Sp3-knockdown cancer cells." (PMID 36615262, 2022). "Through phosphatidylserine (PS) and intact EGFR kinase activity presented by MVs, EGFR-positive MVs could transmit cancer cell-derived EGFR signals to activate MAPK and Akt pathways in human umbilical vein endothelial cells (HUVECs)." (PMID 35158999, 2022). "Therefore, targeting EGFR (proteins that attach to epidermal growth factors) has been one of the effective cancer therapies." (PMID 35685897, 2022). "Therefore, discovery of novel EGFR inhibitors is of great significance for the treatment of malignant tumors." (PMID 36176072, 2022). "The R13 aptamer was obtained through screening against cancer cells overexpressing EGFR." (PMID 35213974, 2022). "The epidermal growth factor receptor (EGFR) belongs to the receptor tyrosine kinase (TK) family and plays an important role in the cancer progression as v-ErbB oncogene present in the avian erythroblastosis virus that has proved to be a mutant homolog of the human EGFR." (PMID 35769445, 2022). "Therefore, we suggest that boron clusters own the affinity for EGFR, demonstrating as important feature for the transport of drugs into the cancer cells (will be published soon)." (PMID 36293047, 2022). "The gain-of-function alterations in EGFR, such as substitution mutations, deletions and insertions, and high levels of cell-surface EGFR expression have been proven to have a crucial role in sustaining cancer cell proliferation, growth and survival, and cancer progression." (PMID 36185288, 2022). "In contrast to platinum-based chemotherapy, patients with EGFR-mutant cancers showed >70% radiological response times and statistically significantly improved PFS when treated with first-generation (erlotinib and gefitinib) or second-generation (afatinib) EGFR TKIs." (PMID 36499382, 2022). "So, the ethyl acetate fraction of T. sanguinea may serve as a rich source of EGFR inhibitors that act as a line of defense against cancer." (PMID 35807354, 2022). "Nimotuzumab is a humanized anti-EGFR antibody registered for several cancer indications." (PMID 35937253, 2022). "Keeping this in mind, and regarding the lack of growth factors in the media due to the starved context, the presence of EGF at the ULD of 27 CH could have reinforced the inhibition of the EGFR pathway, which is rightly involved in cancer-cells metabolism." (PMID 35682738, 2022).